MTOR (mechanistic target of rapamycin kinase)
Diseases named in the same sentence as MTOR in open-access papers (continued):
Sharing a sentence is not in itself a finding about the gene and the disease.
cervical carcinoma (continued). "A study on combination therapy targeting activated ERBB2 and PIK3CA mutations in cervical cancer found that the majority of cervical tumors could benefit from existing ERBB2/PIK3CA/AKT/mTOR-targeted drugs." (PMID 35778737, 2022). "Moreover, the prognosis of cervical cancer patients was associated with the status of the PI3K/AKT/mTOR pathway." (PMID 34356619, 2021). "In this study, we identified that patients with previously treated, locally advanced or metastatic cervical cancer harboring mutations in the PI3K/AKT/mTOR pathway achieved meaningful clinical benefit from a number of novel therapeutics administered in a phase I cancer center." (PMID 25426553, 2014). "Activation of mTOR signaling pathway is associated with cell survival in cervical cancer cells." (PMID 23056046, 2012). "Receptor tyrosine kinases (RTKs) and PI3K-Akt-mTOR signaling play essential roles in multiple adverse biological behaviors including tumorigenesis and progression and are associated with poor prognosis and therapeutic resistance for several types of malignancy including cervical cancer." (PMID 39282148, 2022). "Moreover, human papillomavirus, the most common cause of cervical cancer in women, has been identified as an activator of the mTOR signalling cascade and the cytopathic effect of the infection on cervical epithelium results in balloon-like cells similar to those observed in Type II FCD." (PMID 24735483, 2014). "Mechanistically, FOXK2 promotes lipid metabolic reprogramming in cervical cancer by interacting with the mTOR/DRP1 signaling axis." (PMID 40641601, 2025). "In contrast, sufentanil induces apoptosis in cervical cancer cells through the PI3K/AKT/mTOR signaling pathway." (PMID 40129947, 2025). "A flavonoid called licochalcone A (LiclA), which was isolated from the Batalin root of Glycyrrhiza inflata, inhibits the PI3K/AKT/mTOR signaling pathway in human cervical carcinoma lineages, triggering autophagy and cell death." (PMID 40717210, 2025). "β-D-glucan (LNT) from L. edodes induced Ca2+-dependent autophagy through the PI3K/Akt/mTOR pathway while promoting apoptosis in cervical cancer cells, and autophagy inhibition further enhanced its cytotoxicity." (PMID 41488566, 2025). "In light of these, we sought to elucidate the impact of PPP1R13L knockdown and overexpression on the PTEN/AKT/mTOR pathway and its downstream glycolytic enzymes in cervical cancer cells." (PMID 40014097, 2025). "This suggests that the overactivation of the AKT/mTOR axis contributes to cervical cancer progression and resistance to cellular stress." (PMID 40647429, 2025). "In our investigations into the underlying mechanisms of cervical cancer progression, we showed that GJB5 is integral to the activation of the Akt-mTOR signaling pathway." (PMID 40537499, 2025). "Recognizing the Akt-mTOR pathway as a key driver of cervical cancer malignancy, we focused our investigation on this pathway." (PMID 40537499, 2025). "Given the potential involvement of the Akt-mTOR pathway in GJB5-mediated cervical cancer cell progression in vitro, we examined the activation status of this pathway." (PMID 40537499, 2025). "Luan Y., Zhang W., Xie J., Mao J. CDKN2A inhibits cell proliferationand invasion in cervical cancer through LDHA-mediated AKT/mTOR pathway." (PMID 40584241, 2025). "One of the most extensively studied targeted approaches for HPV-independent cervical cancer is the inhibition of the PI3K/Akt/mTOR pathway." (PMID 41155343, 2025). "NVP-BEZ235 (Dactolisib) acted as a dual PI3K/mTOR inhibitor and was shown to inhibit cervical cancer cell proliferation while inducing apoptosis in cellular assays." (PMID 40777026, 2025).
cervical carcinoma (continued). "It is also worth noting that apart from the inhibition of mTOR signaling, silibinin activates the Akt pathway in cervical cancer cells." (PMID 39836338, 2025). "Early prospective data in cervical cancer come primarily from the dual PI3K/mTOR inhibitor WX390 combined with the PD-1 inhibitor toripalimab." (PMID 41155343, 2025). "The most significant tumor reduction of −65%, with the response still ongoing for more than a year after the data cut-off, was observed in a cervical cancer patient with ErbB2 overexpression and additional PIK3CA, AKT, and mTOR mutations." (PMID 39908697, 2025). "Targeting the PI3K/mTOR pathway in HPV-independent cervical cancer should still be regarded as experimental, with biomarker-driven prospective trials needed before it can be integrated into routine practice." (PMID 41155343, 2025). "Silencing or knocking out Gαi3 significantly inhibited these processes and reduced Akt-mTOR activation, suggesting its role in promoting cervical cancer progression." (PMID 40537499, 2025). "The development and progression of HPV-independent cervical cancer rely profoundly on the PI3K/Akt/mTOR, WNT/β-catenin, and Hippo/YAP signaling pathways." (PMID 41155343, 2025). "Next, to detect the role of AKT/mTOR signaling in RACK1‐promoted fatty acid synthesis metabolism in cervical cancer cells, we treated CC cells with SC79 (Akt activator)." (PMID 39425259, 2025). "We demonstrated that PPP1R13L enhances cell proliferation, cell cycle, EMT, and glycolysis in cervical cancer cells by modulating the PTEN/AKT/mTOR pathway." (PMID 40014097, 2025). "Propofol can inhibit the HOTAIR-mediated mTOR/p70S6K pathway in cervical cancer, thereby inhibiting tumor enlargement and cell viability, and promoting apoptosis." (PMID 40309242, 2025). "Collectively, these 2024–2025 reports constitute the core clinical signal for PI3K/mTOR targeting in cervical cancer, with ongoing studies increasingly enriching for HPV-independent biology." (PMID 41155343, 2025). "Activation of the AMPK/mTOR signaling pathway can activate autophagy, which is one of the mechanisms of cell death in cervical cancer." (PMID 40309242, 2025). "GJB5 knockdown or knockout led to diminished phosphorylation of Akt and S6 kinase, whereas GJB5 overexpression correlated with increased Akt-mTOR signaling in primary human cervical cancer cells." (PMID 40537499, 2025). "Akt-mTOR signaling hyperactivation is a critical driver of cervical cancer malignancy and progression due to its pivotal role in regulating cell growth, proliferation, and survival." (PMID 40537499, 2025). "For instance, in preclinical studies on cervical cancer, the mTOR inhibitor RAD001 enhanced radiotherapy-induced PD-L1 expression." (PMID 40725100, 2025). "Elevated expression levels of phosphorylated PI3K, AKT, and mTOR proteins have been observed in cervical cancer tissues compared to adjacent or preinvasive lesions." (PMID 40647429, 2025). "Searching further for the related mechanisms, a recent study indicated that SPAG5 regulated the sensitivity to taxol (aka., paclitaxel), a standard chemotherapy for TNBC, in cervical cancer cells (HeLa and SiHa) through altering mTOR activity." (PMID 38610947, 2024). "It suppresses the proliferation of cervical cancer cells and stem cells, and suppresses tumorigenicity in mice, mechanisms that are intricately linked to the modulation of the AKT/mTOR signaling pathway." (PMID 39103348, 2024). "ERBB3 modulates PI3K/Akt/mTOR pathway activation to alter the epithelial–mesenchymal transition in cervical cancer." (PMID 39075562, 2024). "Isoflurane not only upregulated LC3-II/I, Beclin-1, and ATG7 and downregulated p62 but also induced oxidative stress and activation of the AMPK/mTOR pathway to promote apoptosis and autophagy and inhibit the proliferation of cervical cancer cells." (PMID 38482052, 2024). "It was postulated that mTOR activation protected cervical cancer cells from apoptosis under taxol treatment." (PMID 38610947, 2024).
cervical carcinoma (continued). "Allicin inhibits biological activities of cervical cancer cells through down‐regulating circEIF4G2/HOXA1/AKT/mTOR." (PMID 38628206, 2024). "Allicin depresses biological activities of cervical cancer cells through down‐regulating circEIF4G2/HOXA1/AKT/mTOR." (PMID 38628206, 2024). "ADRA2A promotes senescence and apoptosis through the inhibition of the PI3K/Akt/mTOR pathway in cervical cancer." (PMID 38903083, 2024). "First, we examined the expression of PIK3CA, a gene related to the PIK3/AKT/mTOR signaling pathway, across various cervical cancer cell lines." (PMID 39590348, 2024). "In contrast to previous reports, this study focuses on the inhibitory effects of AM on the AKT/mTOR pathway, leading to a reduction in cell proliferation in cervical cancer cells." (PMID 38281034, 2024). "The expression of seven hub genes in the PI3K/AKT/mTOR pathway were increased in cervical cancer: EIF4EBP1, GSK3B, HRAS, KRAS, NRAS, PIK3CB and PIK3R2." (PMID 36911370, 2023). "Given that the AKT/mTOR signaling pathway is ubiquitously responsible for cell survival in tumor cells, the new discovery implied a potential target against cervical cancer." (PMID 37566043, 2023). "The PI3K/AKT/mTOR signaling pathway is responsible for inhibiting autophagy in human cervical cancer cells by miR-338-3p." (PMID 36726491, 2023). "The molecular expression level and phosphorylation levels of PI3K, mTOR, and 4EBP1D proteins in cervical cancer cells with the ADAMTS12 overexpression group were detected by WB." (PMID 37642715, 2023). "Beetroot extracts were shown to reduce expression of mTOR signalling in a HeLa cervical cancer cell line." (PMID 36837811, 2023). "The mechanistic target of Rapamycin (mTOR) is an atypical serine/threonine kinase that plays an important role for several cancers, including cervical cancer." (PMID 37510286, 2023). "p-mTOR-expression-positive cervical cancers seem more likely to retain ER expression, and expression of combined features seems to describe a subset of cervical cancers with distinct clinical behavior." (PMID 37623437, 2023). "Here, FNBP1 was confirmed to play a crucial role in maintaining constitutive FAK/PI3K/AKT/mTOR survival signaling in cervical cancer cells." (PMID 37566043, 2023). "In cervical cancer, underlying infections with high-risk human papillomavirus (HPV) provide a particularly strong rationale for mTOR inhibition, as the mTOR pathway appears to play a key role in virus/host cell crosstalk via oncoproteins E6 and E7." (PMID 37623437, 2023). "Surprisingly, the combination of cisplatin and DHODH inhibition significantly downregulated the mTOR pathway activity in our study, which is critically involved in inducing ferroptosis in cervical cancer cells." (PMID 36672495, 2023). "Expression of p-mTOR demonstrates a significant correlation with ER expression across tumor stages and is associated with loss of PTEN in a preclinical cervical cancer model." (PMID 37623437, 2023). "Our study found that ADAMTS12 overexpression in cervical cancer cells upregulated the phosphorylation levels of mTOR and 4E-BP1." (PMID 37642715, 2023). "Other researchers reported that luteoloside inhibited proliferation and modulated apoptosis by mitogen-activated protein kinase (MAPK) and mammalian target of rapamycin (mTOR) signaling pathways in human cervical cancer." (PMID 36838737, 2023). "EGFR/PTEN/mTOR-pathway activation and ER expression appear closely intertwined in cervical cancer, as previously observed in other solid tumors." (PMID 37623437, 2023).
cervical carcinoma (continued). "While cervical cancers otherwise seemingly tend to lose ER expression with increasing tumor stage, p-mTOR-expressing cervical cancers appear to be more likely to retain ER expression." (PMID 37623437, 2023). "In line with the available literature, a relevant subgroup of cervical cancers appears to harbor EGFR/PTEN/mTOR-pathway alterations, which, as we demonstrated, correlate with ER expression." (PMID 37623437, 2023). "Lentiviral SLC5A3 overexpression construct transduction upregulated the cellular myo-inositol level and promoted Akt-mTOR activation, enhancing cervical cancer cell proliferation and migration." (PMID 37324953, 2023). "The Akt-mTOR cascade was inhibited in sh-SLC5A3 AAV-injected cervical cancer xenograft tissues and SLC5A3 KO xenograft tissues." (PMID 37324953, 2023). "It was also demonstrated that UBE2C plays a pivotal role in the regulation and activation of the mTOR/PI3K/AKT pathway in cervical cancer." (PMID 35124721, 2022). "Akt-mTOR activation in primary cervical cancer cells was significantly reduced after Gαi3 silencing or KO, but was augmented following Gαi3 overexpression." (PMID 36263185, 2022). "It was found that miR-338 can regulate the PI3K/AKT/mTOR pathway to inhibit autophagy in cervical cancer, suggesting that miR-338 can be used as a therapeutic target for cervical cancer." (PMID 35883139, 2022). "FHL2 knockdown downregulated the expression of key proteins in the PI3K/AKT/mTOR signaling pathway, thereby promoting apoptosis and inhibiting the proliferation of cervical cancer cells." (PMID 36004205, 2022). "Complementing our findings, previous studies have reported perturbations in PIK3CA, an oncogene part of the ERBB2/PI3K/AKT/mTOR pathway with a battery of druggable targets, present in over 50% of cervical tumor and cervical cancer cell lines." (PMID 36201462, 2022). "inhibited the glycolysis process of cervical cancer cells through the mTOR inhibitor AZD8055 to fight against the unlimited proliferation of tumor cells." (PMID 36313645, 2022). "And the expression of p-mTOR on cervical cancer was significantly higher than normal cervical tissue." (PMID 35477450, 2022). "In combination with conventional chemotherapy, RA methyl ester (RAME) was found to synergistically inhibit mTOR/S6K1 in cervical cancer cell lines (Henrietta Lacks)." (PMID 36365218, 2022). "Many studies have found that the destruction of mTOR leads to the suppression of the cell cycle and angiogenesis, thereby inhibiting the development of cervical cancer." (PMID 35517856, 2022). "Propofol has been found to reduce tumor size and suppress cell proliferation as well as induce cell apoptosis via inhibition of HOTAIR and modulation of mTOR/p70S6K pathway in cervical cancer." (PMID 36438563, 2022). "LINC00861 had an inhibitory function in cervical cancer cells by regulating PTEN/AKT/mTOR signaling pathway." (PMID 36105083, 2022). "Baicalein inactivated AKT and mTOR in cervical cancer cells through upregulation of circular RNA (circHIAT1) and inhibition of miR-19a-3p." (PMID 35955525, 2022). "For example, treatment with rapamycin (mTOR inhibitor) blocks angiogenesis and enhances autophagy in cervical cancer cell lines." (PMID 36354662, 2022). "Streptomyces sp metabolite(s) triggers apoptosis and autophagy of cervical cancer cells by down-regulating mTOR." (PMID 36139919, 2022). "Along this line, overexpression of miR-202-5p in cervical cancer reduced PIK3CA gene expression as well as the activation of PI3K/AKT/mTOR signaling pathway, which suppressed proliferation, invasion, and EMT." (PMID 35682549, 2022). "Here we found that SKI-V potently inhibited Akt-mTOR activation in primary cervical cancer cells, and restoring Akt activation by caAkt1 ameliorated SKI-V-induced cytotoxicity in cervical cancer cells." (PMID 35541904, 2022).
cervical carcinoma (continued). "The newly generated database IMPAGT revealed the existence of immune dysregulation dynamics and the specific enrichment of the PI3K/Akt/mTOR signaling pathway in the tumor immune microenvironment of cervical cancer with high tumor budding." (PMID 36354662, 2022). "Several groups also used NVP-BEZ235 and new 1,3,5-triazine derivatives to double block PI3K/mTOR signaling pathway to inhibit the proliferation of cervical cancer cells, so as to enhance the therapeutic response." (PMID 36313645, 2022). "These small-molecule inhibitors support the inappropriate activation of the PI3K/Akt/mTOR signaling pathway in malignancies in cervical cancer." (PMID 36354662, 2022). "Butein, a bioactive flavonoid isolated from numerous native plants, reduced the phosphorylation of PI3K, Akt, and mammalian target of rapamycin (mTOR) expression and contributed to the inhibition of the tumor growth of HeLa cervical cancer cells." (PMID 35214097, 2022). "BAI also inhibited cell proliferation via blocking of the mTOR/p70S6K pathway and suppressed EMT pathway-associated migration through the TGFβ pathway in cervical cancer HeLa cells." (PMID 36118088, 2022). "Previous study has further revealed that miR-99b-5 expression suppresses mRNA and protein levels of mTOR, PI3K, AKT and p70S6, thereby inhibiting PI3K/AKT/mTOR signaling in human cervical cancer." (PMID 35328346, 2022). "Gαi3 depletion and Akt-mTOR inactivation were detected in Gαi3-silenced/-KO cervical cancer xenograft tissues." (PMID 36263185, 2022). "Akt-mammalian target of rapamycin (mTOR) overactivation is essential for cervical cancer progression 63-65." (PMID 35541904, 2022). "In contrast, the circTPCN/miR-634/mTOR regulatory pathway has been shown to be involved in cervical cancer tumorigenesis." (PMID 36428613, 2022). "The mTOR (mammalian Target of Rapamycin 1)/S6K1 (ribosomal protein S6 kinase 1) signalling pathway was found to be typically active in cervical cancer cells and acts as a biological target during treatment." (PMID 36365218, 2022). "Reducing the SRSF3 level can restrain the viability and metastasis of cervical cancer cells via restraining the PI3K/AKT/mTOR signaling pathway." (PMID 36237584, 2022). "Taken together, we demonstrate that GCP induces cell cycle G2/M-phase arrest, apoptosis, and autophagy by acting on the PI3K/AKT/mTOR signaling pathways in cervical carcinoma cells." (PMID 34093198, 2021). "SNX-2112 remarkably enhanced TRAIL-induced cytotoxicity, promoted the accumulation of reactive oxygen species (ROS) and disrupted Akt/mTOR signaling pathway in cervical cancer cells." (PMID 34112144, 2021). "Here, we demonstrated for the first time that silencing CD155 promotes the autophagic flux of cervical cancer cells via regulation of the mTOR pathway." (PMID 34164340, 2021). "Accordingly, these data indicated that knockdown of DIAPH3 inhibited the proliferation of cervical cancer cells through inactivating the mTOR signaling pathway." (PMID 34659408, 2021). "A23187 exerted an antiproliferative effect on cervical cancer cells through suppressing AMPK/mTOR signaling activity." (PMID 34067321, 2021). "The depletion of UBE2C reduced cervical cancer cell proliferation by inhibiting the mTOR/PI3K/AKT pathway." (PMID 34858987, 2021). "In our study, we firstly explored the notion that knockdown of DIAPH3 inhibits the proliferation of cervical cancer cells through inactivating the mTOR signaling pathway." (PMID 34659408, 2021). "For example, AMPK activators, which decrease mTOR activity and increase autophagy, suppress cervical cancer cell growth by impairing protein synthesis of DVL3, a positive regulator in Wnt/β-catenin signaling." (PMID 33668092, 2021).